IL18 (interleukin 18)
Diseases named in the same sentence as IL18 in open-access papers (continued):
Sharing a sentence is not in itself a finding about the gene and the disease.
cancer (continued). "Interleukins, such as IL-2, IL-12, IL-15, IL-18, and IL-21, glucocorticoids, such as cortisone acetate and hydrocortisone, and ascorbic acid can promote the ex vivo proliferation of NK cells in healthy people or cancer patients." (PMID 39286242, 2024). "An important component of inflammation in our bodies is the inflammasome complex, which converts pro versions of cytokines like IL-1β and IL-18, which aids in cancer progression; thus, investigating various inflammasome inhibitors such as MCC950, CY-09, and others is critical." (PMID 37715239, 2023). "Furthermore, we previously demonstrated the effectiveness of cancer immunotherapy using IL18 to augment immune checkpoint inhibitors." (PMID 38139000, 2023). "Further study is needed to determine whether IL18 suppresses or promotes cancer progression through Ly6a." (PMID 38139000, 2023). "Secreted IL-18 acts on cancer cells and promotes cancer malignancy." (PMID 37047826, 2023). "Finally, the potential of targeting the P2RX7/IL-18 pathway in combination with classical immunotherapies to fight cancer is discussed." (PMID 37298187, 2023). "Although the remarkable antitumor efficacy of IL12 has yet to be replicated in preclinical human models, preclinical studies on the combination of IL12, IL15, and IL18 might represent ideal approaches to generating NK and DCs for cancer therapy." (PMID 36968220, 2023). "Indeed, IL-18BP is present physiologically at high levels and has been shown to be further increased in several cancers, inhibiting even more IL-18 signaling." (PMID 37298187, 2023). "Recently more and more studies have focused on the effects of IL18 on cancer." (PMID 36707882, 2023). "An increasing number of studies have demonstrated a relationship between IL18 and cancer." (PMID 38139000, 2023). "IL18 is an anti-tumoral factor or an oncogenic factor in different type of cancers." (PMID 36707882, 2023). "On the other hand, pyroptosis is accompanied by the release of inflammatory mediators, such as IL-1 and IL-18, which might facilitate cancer development and progression." (PMID 36941988, 2023). "The antitumor potential of IL-18 has also been evaluated in cancer patients." (PMID 37298187, 2023). "The role of IL-18 has been studied in several types of cancer." (PMID 37298187, 2023). "Building on a previous report linking IL18 deficiency to metabolic disorders and depressive-like behavioral changes, we describe here the relationship between IL18 and cancer tumorigenesis, and the potential for IL18 treatment of cancer immunotherapy in combination with immune checkpoint inhibitors." (PMID 38139000, 2023). "PM2.5-exposure has also been shown to induce an AhR-dependent transcriptional activation of transmembrane serine protease 2 (TMPRSS2) and subsequent expression of the IL-1 family member IL-18 that may promote cancer progression." (PMID 37696458, 2023). "On the other hand, IL-18 and IL-21 contribute to the effector function of NK cells against cancers." (PMID 37501379, 2023). "The acidic microenvironment around cancer cells stimulated the expression of IL-18, which in turn might be correlated with the IFN-γ mediated immune response." (PMID 37719323, 2023). "Further study is required to determine whether IL18 suppresses or promotes cancer development through Ifi16." (PMID 38139000, 2023). "The increased secretion of IL18 may in turn promote cell proliferation, proinflammation, and cancer progression." (PMID 36975376, 2023). "RanBP1 can modulate the cancer microenvironment by regulating the cytokine IL-18." (PMID 37047826, 2023). "The role of interleukin 18 in cancer development is not fully understood." (PMID 36012171, 2022). "In the risk score model, the higher the expression of IL-18, the longer the DFS, suggesting that IL-18 might be involved in the process of inhibiting cancer cell growth, and increasing its expression could help improve the prognosis." (PMID 36675746, 2022).
cancer (continued). "Thus, IL-18 inhibition suppresses metastasis because it neutralizes the adhesiveness of cancer cells to the endothelium." (PMID 36678726, 2022). "Protective effects of IL-18 in cancer have been reported in different murine models." (PMID 35865545, 2022). "Recently, a decoy-resistant IL-18 was developed for application in cancer immunotherapy." (PMID 35811828, 2022). "Activation of the NLRP3 inflammasome leads to the release of the proinflammatory cytokines IL-1β and IL-18, which may contribute to cancer development." (PMID 35707534, 2022). "Authors plan to investigate if IL-6, IL-8 and IL-18 hypersecretion and reduced secretion of IL-17 in HIV, TB mono-infections and HIV/TB co-infections can predict morbidity and mortality associated with lung and other forms of cancer." (PMID 35804391, 2022). "IFN-γ induced by IL-18 could also stimulate upregulation of PD-L1 on tumors cells, providing a rationale for combining IL-18 and PD-1 checkpoint inhibitors in cancer immunotherapy." (PMID 35529882, 2022). "MYD88 is also an IL-18 signaling mediator, whose absence may promote cancer by inhibiting the activity of an IL-18-dependent pathway." (PMID 35740541, 2022). "IL-18 has long been proposed as a potential candidate for cancer treatment." (PMID 35811828, 2022). "Intraperitoneal or intrathecal administration of MCC950, a specific NLRP3 inflammasome inhibitor, alleviated mechanical allodynia, and decreased IL-1β and IL-18 release in the lumbar dorsal spinal cord in cancer-induced bone pain and oxaliplatin-induced neuropathy, respectively." (PMID 36324872, 2022). "In the cancer-induced bone pain model, IL-1β and IL-18 were detected predominantly in neurons." (PMID 36324872, 2022). "Nevertheless, many studies show that the use of IL18 binding protein (IL18BP, a soluble protein that binds to IL18), which will neutralize the effects of this interleukin, may have a positive therapeutic effect on cancer." (PMID 36012171, 2022). "This study suggests that IL‐18 possesses an anti‐cancer property." (PMID 34196131, 2022). "Moreover, both strains triggered interleukin 18 gene expression, normally inhibited in Caco-2 (cancer) cells." (PMID 35694291, 2022). "Inflammasomes regulate the activity of caspase-1 and the maturation of IL1β and IL-18, which act as innate immune system sensors and receptors in various infections, cancer, and other diseases, among which the NLRP3 inflammasome has been well characterized to date." (PMID 35457287, 2022). "Overexpression of pro-inflammatory cytokines such as IL-1β and IL-18 may promote cancer progression, increasing an excessive inflammatory response." (PMID 34681768, 2021). "IL-18 has also been indicated to have an important role in other cancer types." (PMID 33660570, 2021). "Moreover, the inflammatory mediator IL-18 is known to accumulate in cancer patients with the ability to fine-tune the activation status of NK cells, depending on the amount of IL-18." (PMID 33540625, 2021). "IL-18 could also be a potential therapeutic target in multiple myeloma, indicating its potential role in cancer development; nevertheless, its role in CRC still needs to be investigated." (PMID 33660570, 2021). "IL-18 is an immunoregulatory cytokine with anti-cancer effect in many types of cancers." (PMID 34114949, 2021). "Our study suggested that IL-18 can be a new potential target for cancer immunotherapy for CRC." (PMID 33660570, 2021). "These and previous studies indicate that inflammasomes have diverse roles in cancer with some cancers benefiting from IL‐1β and IL‐18, whereas in others, the IL‐1 signaling pathway promoted cancer growth (Karki & Kanneganti, 2019; Karki, Man, & Kanneganti, 2017)." (PMID 32027447, 2020). "IL‐18 was reported to perform an oncogenic role in supporting cancer cell survival and invasion." (PMID 32347623, 2020).
cancer (continued). "Indeed, NLRP6 and IL-18 are strongly involved in the regulation of the microbiome, which is now recognized as a critical player in colon inflammation favoring cancer." (PMID 33255437, 2020). "Moreover, the importance of IL-18BP (IL-18 binding protein), an antagonist of IL-18, should also be considered when analyzing the effects of IL-18 in cancer." (PMID 33261061, 2020). "Indeed, the common mutations to NLRP3 and its downstream mediators varies across cancer types and tissue location; the data on these mutations contradicts the protective findings of NLRP3′s IL-18-mediated downstream activity." (PMID 32098318, 2020). "Moreover, the inflammasome signalling can prime natural killer (NK) cells through IL‐1β or IL‐18 and exert anti‐cancer effects by specialized programmed cell death called pyroptosis and immune regulatory functions." (PMID 32725966, 2020). "Interleukin-18 (IL-18), initially named IFN-γ inducing factor, is a proinflammatory cytokine encoded by the human IL-18 gene and produced by activated macrophages, epithelial cells, osteoblasts, keratinocytes, and most importantly, cancer cells." (PMID 30925760, 2019). "It is possible, however, that combining an IL-18 targeting strategy with additional chemotherapeutic reagents could be a better approach in the treatment of patients with cancer." (PMID 31231372, 2019). "A key feature of HPV-induced carcinogenesis, is that chronic inflammation is one of the main promoters of oncogenic pathway activation, and several studies have shown that the activation of IL-1β and IL-18 proteins by inflammasome increases the progression of different types of cancer." (PMID 31554368, 2019). "Under the condition that IL-18 is harmful, the utilization of IL-18BP to neutralize IL-18 may be a potential therapeutic approach for certain types of cancer." (PMID 31492049, 2019). "One is the establishment of cancer therapy by IL-18-activated human γδT cells." (PMID 30717382, 2019). "The complex interplay among these pathways might determine the final effects of IL-18 on cancer pathogenesis." (PMID 31492049, 2019). "Although γδ T cells act as important effector cells for better prognosis in cancer patients, and this study shows the positive correlation between IL18 and γδ T cells-related genes, it is well known that those genes are also expressed in other effector cells, CD8+ T cells and NK cells." (PMID 31731729, 2019). "These promising results may propel further investigation of the clinical utility of IL-18-based therapy in cancer intervention." (PMID 31492049, 2019). "Intriguingly, IL-18 plays a pro-carcinogenic role in several types of cancer." (PMID 31492049, 2019). "Several cancers including bladder cancer and ovarian cancer and gastrointestinal cancer showed higher levels of IL-18.IL 18 and its receptor (IL18 R) expression in were found to have a role in ovarian epithelial cells either cancerous or normal." (PMID 31554361, 2019). "Another SNP located in the IL-18 promoter is -656 (A/C); however, the effects of different genotypes at IL-18 -656 on cancer risk have not yet been well elucidated." (PMID 30925760, 2019). "On the contrary, IL-18 can compromise host immune responses in favor of cancer evasion." (PMID 31492049, 2019). "The function of IL-18 in cancer could also depend on cytokines present at the site of NK cell activation and maturation." (PMID 31231372, 2019). "Thus, the purpose of this study is to determine the possible role of IL18 and NO and their relation to total oxidative capacity and antioxidants in the development and progression of cancer breast in a group of Egyptian females." (PMID 31554361, 2019). "In addition, we suggest a combination of IL-15, IL-18, and IL-27 in human NK cell culture can lead to increased effectiveness of NK cell-mediated immunotherapeutics against cancers or infectious diseases." (PMID 31277710, 2019). "In another study, we suggested a new cancer immunotherapy using IL-18." (PMID 29514661, 2018).
cancer (continued). "IL-18 has both cancer-promoting and cancer-suppressing functions." (PMID 29599908, 2018). "We previously reported on a novel cancer immunotherapy with IL-18." (PMID 29514661, 2018). "In turn, caspase-1 enhances the proteolytic cleavage and the secretion of the inflammatory cytokines interleukin (IL)-1β and IL-18, leading to infiltration of more immune cells and resulting in the generation and maintenance of an inflammatory microenvironment surrounding cancer cells." (PMID 30619282, 2018). "It is well established that, caspase-1 primarily activates IL-1β and IL-18 in cancer." (PMID 28974683, 2017). "Among those, IL-18 plays both pro-inflammatory and anti-cancer roles in cancer progression." (PMID 28415798, 2017). "Furthermore, the results of a phase I study on the effects of IL-18 administration among advanced cancer patients revealed a large contraction of NK cells after IL-18 treatment." (PMID 28900426, 2017). "In addition, chills and fevers were rare in cancer patients who had an intravenous IL-18 injection, while fever was observed only 3 of 21 cases at doses of 100 and 200 μg kg-1." (PMID 27483370, 2016). "IL-27 similar to other cytokines studied as potential anti-cancer agents, e.g. IL-18 or IL-21, may have a dual role in immune-regulation." (PMID 26657115, 2015). "Composition of intestinal microbiota, however, may also affect cancers distal to the GI track due to the global effect of inflammasome activation and IL-1β or IL-18 secretion." (PMID 24474192, 2014). "On the other hand, IL-18 promotes T helper type 2 (Th2) immune responses that may inhibit recognition of cancer cells by immune cells, increase the adhesion molecules, induce production of angiogenic factors, and promote a prometastatic microenvironment." (PMID 24963217, 2014). "Nonetheless, our knowledge on the effects of IL-18 during human cancer development is still very limited and deserves further clinical investigation prior to considering IL-18 or IL-18BP to be potential therapeutic agents against cancer progression." (PMID 24963217, 2014). "Interleukin (IL)-18 is an 18kd protein that has potential as an anti-cancer agent." (PMID 21935389, 2011). "Our findings indicate that by simultaneously affecting both CD8+ T cells and Tregs, IL-18 may alter the set point of an immune response, underscoring the potential utility of IL-18 as an adjuvant in cancer therapy." (PMID 18818761, 2008). "The rationale for the present study was to determine if IL-18 might present a less toxic alternative to IL-12 as an adjunct for cancer adoptive transfer immunotherapy." (PMID 18818761, 2008). "The data indicate that IL18 polymorphisms do not consistently influence cancer risk." (PMID 41257666, 2025). "Therefore, rGRA6Nt is a novel protein adjuvant that has an unique activity to selectively activate production of both IFN-γ and IL-18 by innate immune cells to potently activate cancer-specific CD8+ cytotoxic T cells and IFN-γ production by both CD4+ and CD8+ T cells." (PMID 40832663, 2025). "This may involve DBMSC-NK cell interaction after DBMSC transplantation in cancer patients, or in vitro by the NK cell adoptive transfer approach where different mechanisms such as IL-18, IFN-ɤ receptors or other mediators may be involved." (PMID 39539962, 2024). "Further attempts were made to investigate how cancer cells could escape the IFN-γ mediated attack stimulated by cancer cells via IL-18 on immune cells in an acidic environment and what role the acidic medium played as an intermediary medium between the interactions of cancer and immune cells." (PMID 37719323, 2023). "Thus, IL-18 in combination with immune checkpoint inhibitors may be a promising strategy for developing next-generation cancer immunotherapy." (PMID 37483629, 2023).
cancer (continued). "When interacting with danger associated molecules (DAMPs) derived from cancer cells, membrane components of innate immunity, such as pattern recognition receptor (PRR), trigger a response of inflammasomes, resulting in activation of caspase-1, which cleaves pro-IL18 and produces IL-18." (PMID 38298540, 2023). "Thus, IL18 is an essential cytokine in inflammatory responses and cancer immunotherapy." (PMID 38139000, 2023). "However, IL-1β and IL-18 are able to promote T cell immunity against cancer in other cases." (PMID 36932407, 2023). "Furthermore, IL-18 can also induce tumoricidal NK cell activity against metastasized colonic tumor cells in the mouse liver, and inflammasome-dependent pyroptosis in cancer cells exerts direct tumoricidal effects." (PMID 35740272, 2022). "Inflammasomes and their effectors such as IL-1β and IL-18 significantly contribute to establishment of inflammation, while the TME is enriched in damage-associated molecular patterns (DAMPs) that have been shown to drive inflammasome activation in both immune and cancer cells." (PMID 36032139, 2022). "IL-18 is a pro-inflammatory and immunomodulatory cytokine of the IL-1 family that is converted from an inactive precursor protein (pro-IL18) by caspase-1-induced cleavage of an N-terminal fragment and may have anti-cancer and oncogenic effects depending on the tissue and cellular environment." (PMID 36743929, 2022). "IL-18, as a member of the IL-1 family of cytokines, is involved in the activation of T cells, NK cells and macrophages, and plays an important role in the process of immunoregulation in various inflammatory and malignant diseases, including pyroptosis and cancer." (PMID 35682857, 2022). "Various studies have confirmed that the NLRP3-mediated release of IL-18 or IL-1β enhances the malignancy of lymphoma, gastric cancer, breast cancer, colon cancer, and glioblastoma via promoting the proliferation of cancer, immunosuppression, angiogenesis, and metastasis." (PMID 34298833, 2021). "It includes seven ligands with pro-inflammatory activity (IL-1α, IL-1β, IL-18, IL-33, IL-36α, IL-36β, IL-36γ), as well as anti-inflammatory cytokines (IL-37 and IL-38), having crucial roles in host-defense responses, but also in inflammatory responses that contribute to cancer development." (PMID 33840390, 2021). "In conclusion, our current study establishes that IL-18–induced eosinophilic inflammation mechanistic pathway may be operational in the pathogenesis of CP-induced development of pathological characteristics cancer phenotype that further progress to malignancy." (PMID 34183442, 2021). "Thus, Pin1 may be critical in balancing the cancer‐promoting and cancer‐suppressing effects of IL‐18." (PMID 32347623, 2020). "However, IL-18 had limited therapeutic efficacy as a single agent in cancer patients." (PMID 31492049, 2019). "IL-18-induced NK cells might be useful for cancer immunotherapy." (PMID 31492049, 2019). "Collectively, IL-18-based immunotherapy might be a promising therapeutic strategy for cancer." (PMID 31492049, 2019). "Open Science Framework: CCL2 and IL18 expressions may associate with the anti-proliferative effect of noncontact electro capacitive cancer therapyin vivo." (PMID 32695310, 2019). "However, aberrantly expressed IL-1β and IL-18 contribute to cancer pathology." (PMID 31492049, 2019). "Therefore, IL-18 in combination with immune-checkpoint therapy might be a potential treatment for the early stages of cancer in humans." (PMID 30717382, 2019). "Based on results demonstrating the immunostimulatory role of IL-18, the authors concluded that the balance between the effects of IL-18-mediated antitumor immunity and its promotion of cancerous cell invasion could have favorable effects in the host by blocking NF-κB expression in cancer cells." (PMID 29315242, 2018). "Furthermore, IL-18-activated NK cells or Th1 cells could be developed as immune cell therapies against cancer." (PMID 28955343, 2017).